CA7 (carbonic anhydrase 7)
Description:
Reversible hydration of carbon dioxide.
Synonyms: CA-VII; CAVII
Tractability: Small molecule: an approved drug acts on it; a structure with a bound ligand is known; a high-quality ligand is known; it belongs to a druggable protein family. PROTAC: a small molecule that binds it is known.
Target class: Enzyme; Lyase
Chemical probes: DAIDZEIN, LUTEOLIN, TILIROSIDE
Gene: Protein-coding gene on chromosome 16 (66,844,414 to 66,854,153, forward strand). Ensembl gene ENSG00000168748.
Subcellular location: Cytoplasm
Subcellular location (Human Protein Atlas): Cytosol; Golgi apparatus
Pathways (Reactome):
Metabolism: Reversible hydration of carbon dioxide
Gene Ontology:
Molecular function: carbonate dehydratase activity; zinc ion binding
Cellular component: cytoplasm; cytosol
Genetic constraint (gnomAD): Loss-of-function variants: 10 observed, 29.95 expected, observed/expected ratio (o/e) 0.33, 90% interval 0.2 to 0.57. The upper end of that interval is the gene's LOEUF score, 0.57, which puts it in group 2 of 6, group 1 being the genes least tolerant of losing a copy. Missense variants: 211 observed, 357.44 expected, observed/expected ratio (o/e) 0.59, 90% interval 0.53 to 0.66. Synonymous variants: 125 observed, 137.45 expected, observed/expected ratio (o/e) 0.91, 90% interval 0.79 to 1.05.
Homologues: Orthologues: chimpanzee CA7 (100% identical), macaque CA7 (100% identical), mouse Car7 (95% identical), guinea pig CA7 (94% identical), dog CA7 (92% identical), rabbit CA7 (91% identical), rat Car7 (91% identical), pig CA7 (84% identical), tropical clawed frog ca7 (72% identical), zebrafish ca7 (70% identical), Caenorhabditis elegans cah-5 (39% identical), Drosophila melanogaster CAH9 (33% identical), and 12 more. Paralogues in human: CA2 (56% identical), CA13 (53% identical), CA5B (51% identical), CA1 (50% identical), CA3 (49% identical), CA5A (49% identical), CA8 (41% identical), CA12 (38% identical), CA14 (36% identical), CA6 (36% identical), CA9 (35% identical), CA10 (33% identical), and 2 more.
Diseases named in the same sentence as CA7 in open-access papers:
CA7 is named in the same sentence as 34 diseases in open-access papers, as found by Europe PMC text mining. Sharing a sentence is not in itself a finding about the gene and the disease. The quoted sentences say what the papers report.
colorectal cancer (8 papers, 2014 to 2023). A primary or metastatic malignant neoplasm that affects the colon or rectum. "Its tumor-suppressive potential was identified in colorectal cancer as reduced CA7 level was associated with shorter disease-specific survival." (PMID 28487351, 2017). "The expression of CA7 was downregulated in colorectal cancer and correlated with disease progression." (PMID 35511361, 2022). "CA7 was indicated as an important suppressor gene for the classification of normal and colorectal cancer tissues in this study." (PMID 24959000, 2014). "Furthermore, four genes, ABCG2, PADI2, CA7, and TGFBI, have been verified in previous studies as potentially correlated with colorectal cancer." (PMID 28229027, 2017). "Nevertheless, the expression and clinical relevance of CA7 in colorectal carcinoma (CRC) has not been investigated." (PMID 25885898, 2015).
colon cancer (7 papers, 2015 to 2025). "Indeed, CA7 is associated with poor prognosis and disease progression, particularly in the early stages of colon cancer." (PMID 28229027, 2017). "CA7 expression exhibited a strong correlation with the Act_B (rho = 0.199, p = 1.82 × 10−5) and Neutrophils (0.263, p = 1.28 × 10−8) levels in colon cancer and with the Act_B (rho = 0.127, p = 0.102) and Neutrophils (rho = 0.259, p = 0.000739) levels in rectal cancer." (PMID 37895185, 2023). "The TCGA results indicated that SPIB, KRT24, PHLPP2, PLP1, BEST4, CA7, and C11orf86 were all downregulated, while KRT80, SLC39A10, AJUBA, FOXQ1, and CLDN1 exhibited upregulated levels in colon cancer." (PMID 32633726, 2020). "About colon cancer data set DIEXF, GUCA2A, CA7, and IGHA1 key genes with the accuracy of 87.39 and precision of 85.45 were selected." (PMID 29563929, 2017). "CA-7 was found to be downregulated showing weak CA7 ISH signal in normal colon and no detectable signal in the analyzed adenomas and colon cancer FFPE tissue samples." (PMID 26208990, 2015). "No CA7 ISH signal was detected in adenoma and colon cancer tissue." (PMID 26208990, 2015).
adenoma (5 papers, 2010 to 2023). A neoplasm arising from the epithelium. "CA7 was also found to be downregulated not only in carcinoma, but in adenoma samples." (PMID 23155391, 2012). "In situ hybridization for two selected transcripts (CA7, CXCL1) was performed on NAT (n = 3), adenoma (n = 3) and CRC (n = 3) FFPE samples." (PMID 26208990, 2015). "The genes CA2, CA7, and ITM2C collectively play critical roles in CRC progression, with CA2 influencing adenoma characteristics and cell proliferation, CA7 acting as a tumor suppressor gene, and ITM2C likely sharing similar tumor-suppressive properties with its family member ITM2A." (PMID 37895185, 2023).
astrocytomas (3 papers, 2015 to 2025). "In addition, it has been shown that upregulated expression of CA7 was associated with poor prognosis of patients with astrocytomas." (PMID 25885898, 2015).
breast carcinoma (2 papers, 2017 to 2023). "Notable exceptions to this pattern are CA4, which is detected only in breast cancer endothelial cells, and CA7, which is expressed exclusively in cancer-associated fibroblasts and myeloid cells." (PMID 37098526, 2023). "Top HBF + BPA-dysregulated genes (ALDH1B1, ASTL, CA7, CPLX4, KCNV2, MAGEE2 and TUBA3E) are associated with poor overall survival in The Cancer Genomic Atlas (TCGA) human breast cancer cohort (n = 1082)." (PMID 28487351, 2017). "To gain clinical significance, using The Cancer Genomic Atlas (TCGA) breast cancer cohort, we dichotomized 1082 breast cancer subjects into two groups based on the expression of the seven genes (ALDH1B1, ASTL, CA7, CPLX4, KCNV2, MAGEE2 and TUBA3E)." (PMID 28487351, 2017). "We took advantage of the publicly available RNA-seq and survival data from TCGA and determined that seven differentially expressed genes (ALDH1B1, ASTL, CA7, CPLX4, KCNV2, MAGEE2 and TUBA3E) could be involved in breast cancer development, especially in Caucasian female patients with ER positivity." (PMID 28487351, 2017). "Interestingly, expression of four genes (ALDH1B1, ASTL, CA7 and TUBA3E) of the seven gene panel was significantly different between the two groups of human breast cancer subjects (data not shown)." (PMID 28487351, 2017).
rectal cancer (2 papers, 2022 to 2023). A primary or metastatic malignant neoplasm that affects the rectum. "Decreased expression of CA7 has been found in rectal cancer, rectal adenocarcinoma and CRC." (PMID 35114976, 2022).
colorectal adenoma (1 paper, 2015). An adenoma that arises from the colon or rectum. "In situ hybridization could confirm the upregulation of CXCL1 and downregulation of CA7 in colorectal adenomas and tumors compared to healthy controls." (PMID 26208990, 2015).
diffuse astrocytoma (1 paper, 2015). A low-grade (WHO grade II) astrocytic neoplasm. "In addition, the expression of CA7 and its prognostic significance has been demonstrated in human diffuse astrocytomas." (PMID 25885898, 2015).
lymph node metastasis (1 paper, 2015). "Consistently, low levels of CA7 protein were significantly correlated with differentiation grade (p = 0.046), lymph node metastasis (p = 0.003), TNM stage (p = 0.003) and patient death (p < 0.001)." (PMID 25885898, 2015). "Reduced expression of CA7 was significantly correlated with poor differentiation, positive lymph node metastasis, advanced TNM stage and unfavorable clinical outcome not only in the training cohort but also in the validation set." (PMID 25885898, 2015).
Sjogren syndrome (1 paper, 2022). An autoimmune disorder in which immune cells attack and destroy the glands that produce tears and saliva. "CA6 (gustin) and CA7 are both expressed in salivary glands and ameloblasts, and have been linked to Sjogren’s syndrome." (PMID 36404915, 2022).
cancer (12 papers, 2012 to 2025). A tumor composed of atypical neoplastic, often pleomorphic cells that invade other tissues. "Carbonic anhydrases, particularly CA4 and CA7, have been suggested to play important roles in extracellular acidification in cancer." (PMID 35787947, 2023). "CA7 is a member of the carbonic anhydrases gene family, which has been proposed to be related to the pathogenesis of human cancers." (PMID 28229027, 2017). "Of note, in normal colon, the strongest immunostaining for CA7 was predominantly localized in the superficial part of the mucosa, while its expression in carcinomas was diffuse." (PMID 25885898, 2015). "Given that oxidative stress has been implicated in the pathogenesis of a wide spectrum of human cancers including CRC, the reported protective role of CA7 against oxidative stress might support a tumor-suppressing function for this enzyme." (PMID 25885898, 2015). "Although the mechanistic role of CA7 in cancer is not much known, it has been speculated that the absence of the antioxidant property of CA7 could contribute to disease progression." (PMID 28487351, 2017). "Further analysis of an external CRC dataset and various literature sources revealed that CA2, CA7, and ITM2C could act as gene signatures for the early detection of CRC and showed the potential to regulate cell growth and division in a manner that could prevent cancer progression." (PMID 37895185, 2023).
tumor (8 papers, 2014 to 2025). "According to a recently published manuscript from Yang and collaborators analyzing FFPE (n = 379) and fresh frozen CRC (n = 84) tissue samples, CA7 was frequently downregulated in tumor samples both on mRNA and protein levels." (PMID 26208990, 2015). "CA7 mRNA expression was markedly decreased in tumor tissues compared with adjacent normal mucosa tissues (50/59, p < 0.001)." (PMID 25885898, 2015). "In addition, Western blot analysis from an independent set of 25 paired CRC and adjacent normal specimens demonstrated that protein expression of CA7 was significantly downregulated in tumor tissues compared with adjacent normal tissues (18/25, p < 0.001)." (PMID 25885898, 2015). "Downregulation of CA7 transcript along tumor formation and the presence of a large CpG island in the gene’s promoter region raises the theoretical possibility of its epigenetic gene regulation by DNA methylation; further studies are needed to confirm this hypothesis." (PMID 26208990, 2015). "It is evident through the heatmap that maximum downregulation was observed with CA7 and minimum downregulation was observed with GAPDH when compared to the TCGA-CRC (tumor and normal) samples." (PMID 37895185, 2023). "Gelatinase activity was one major GO annotation of these eight genes (CA7, SPIB, GUCA2B, AQP8, IL6R, SPP1, TCN1, and CWH4) and is related to tumor progress and metastasis." (PMID 24959000, 2014).
neurological diseases (2 papers, 2020 to 2021). "CA7 was associated with activity levels during sleep and activity levels during wake, and in previous studies its expression in brain was associated with neurological disorders." (PMID 33075057, 2020).
infection (1 paper, 2013). The state of being infected such as from the introduction of a foreign agent such as serum, vaccine, antigenic substance or organism. "The screen also predicted a role during infection for cytosolic carbonic anhydrase 7, which belongs to a family of enzymes that generate bicarbonate." (PMID 23696731, 2013).
CA7 also shares sentences with these, for which no sentence is quoted: neurodegenerative disease (2 papers); atherosclerosis (1); brain glioma (1); brain tumors (1); colorectal (1); colorectal adenocarcinoma (1); connective tissue diseases (1); epilepsy (1); febrile seizures (1); gastric cancer (1); hepatocellular carcinoma (1); Hypertension (1); interstitial lung disease (1); mixed oligoastrocytomas (1); oligodendroglioma (1); ovarian carcinoma (1); prostate carcinoma (1); rectal adenocarcinoma (1); stomach cancer (1); thyroid carcinoma (1).